MTOR (mechanistic target of rapamycin kinase)
Diseases named in the same sentence as MTOR in open-access papers (continued):
Sharing a sentence is not in itself a finding about the gene and the disease.
prostate carcinoma (continued). "In prostate cancer, high expression of Apelin Receptor (APLNR) activates the PI3K/AKT/mTOR signaling pathway, increasing levels of p-PI3K, p-AKT, and p-mTOR." (PMID 40725100, 2025). "It is worth noting that in cases of prostate cancer, the activation of the phosphatidylinositol-3-kinase (PI3K), protein kinase B (PKB/AKT), and mTOR-dependent pathways facilitates tumour formation, disease progression, and therapeutic resistance." (PMID 39941741, 2025). "In radioresistant prostate cancer models, aberrant activation of the PI3K/AKT/mTOR signaling pathway significantly promotes EMT and the formation of cancer stem cell (CSC) phenotypes." (PMID 40725100, 2025). "In prostate cancer cells, curcumin inhibited MAO-A/mTOR/HIF1α signaling, thus suppressing epithelial-mesenchymal transition, while a synthesized flavonoid derivative with MAO-A inhibiting properties displayed anti-proliferative and anti-metastatic activities." (PMID 39714760, 2025). "When discussing the role of GLP-1 receptor agonists in the regulation of pathways influencing prostate cancer carcinogenesis, it is worth mentioning dipeptidyl peptidase 4 (DPP-4), which also regulates the activity of the ERK1/2- and mTOR-dependent pathway." (PMID 40361502, 2025). "Glutamine metabolism in prostate cancer is also regulated by oncogenes like MYC, androgen receptors (AR), and mTOR, with metabolic tracing studies highlighting glutamine’s role in energy and precursor synthesis." (PMID 41179661, 2025). "In prostate cancer, SLC14A1 downregulation enhances CDK1/CCNB1 and mTOR pathway activity, accelerating tumorigenesis." (PMID 40746552, 2025). "Recent study suggests that AR signaling promotes prostate cancer cell growth by increasing G6PD expression and enhancing flux through pentose phosphate pathway via activation of the mTOR-SREBP1 axis." (PMID 41514554, 2025). "In the treatment of prostate cancer resistance, inhibition of AKT/mTOR will feedback enhance MAPK signaling, and conversely, MEK inhibitors will relieve S6K’s inhibition of IRS1, activate the PI3K-AKT pathway, and lead to compensatory escape." (PMID 41368570, 2025). "In prostate cancer stem cells, sertraline induces autophagy via mitochondrial dysfunction, ROS accumulation, and AMPK activation, leading to suppression of mTOR signaling." (PMID 40874450, 2025). "Previous studies have demonstrated that EpCAM knockdown results in increased sensitivity to chemotherapy and radiotherapy in prostate cancer cells, which is interpreted by inactivation of PI3K/AKT/mTOR signaling." (PMID 38791091, 2024). "These compounds are notably effective against breast, lung, liver, and prostate cancers, exhibiting IC50 values of approximately 121.4 nM against PC-3 and DU-145 cells, primarily through the PI3K/Akt/mTOR, NF-κB, MAPK, and JAK/STAT signaling pathways." (PMID 38276618, 2024). "Treatment of Tan in prostate cancer PC-3 cells leads to suppressed EMT by attenuating Vimentin expression and increasing E-cad level through the PI3K/Akt/mTOR pathway." (PMID 38924029, 2024). "AKT1, mTOR, CASP9, and BCL2 were identified as the top targets involved in the anti-prostate cancer resistance effect of the SR-CR drug pair." (PMID 38326539, 2024). "This rise in glyoxalase enzymes is facilitated by the activation of the PI3K/AKT/mTOR pathway through the PI3K/AKT/mTOR/p-PKM2(Y105)/ERa axis, ultimately propelling prostate cancer progression." (PMID 38785990, 2024). "SR-CR inhibited the Prostate cancer signaling pathway by downregulating the expression of AKT1 and mTOR, and upregulating CASP9, leading to apoptosis in prostate cancer cells." (PMID 38326539, 2024). "KEGG pathway enrichment revealed that cancer-related pathways were widely enriched, with the Prostate cancer pathway ranking first, indicating that SR-CR AKT1, mTOR, and CASP9 were all enriched in the Prostate cancer pathway." (PMID 38326539, 2024).
prostate carcinoma (continued). "Additional research has shown that GLP-1 RAs can inhibit prostate cancer growth by targeting the PI3K/AKT/mTOR and ERK/MAPK pathways and can also suppress pancreatic and prostate cancer cell growth by inhibiting the NF-kB pathway." (PMID 39335195, 2024). "In vitro studies have confirmed the inhibitions of Akt-, mTOR-, and P70S6K-related activities of the flavonoids and certain polyphenolic compounds in breast and prostate cancer cell lines." (PMID 36982245, 2023). "PTEN gene inactivation is observed in many tumor types, including prostate cancer, and can occur by diverse mechanisms, ultimately leading to the constitutive activity of the PI3K/AKT/mTOR pathway." (PMID 36768610, 2023). "In a study involving human prostate cancer cells, KIF18B was shown to promote prostate cancer progression by activating mTOR signaling pathway." (PMID 37957153, 2023). "Among various causes of prostate cancer androgen receptor (AR) signaling, PTEN/PI3K/AKT/mTOR pathway, IL6/STAT3 and STAT5a/b are the most common pathways involved in prostate cancer cell survival and resistance." (PMID 36648960, 2023). "Differently from prostate cancer, mechanistic target of rapamycin (mTOR) protein, a key member of the PI3K-AKT-mTOR signaling pathway frequently hyperactivated in several malignancies, stimulates AR transcriptional activity in HCC." (PMID 37508414, 2023). "We focus on the regulation of glutamine metabolism in prostate cancer through key pathways involving the androgen receptor pathway, MYC, and the PTEN/PI3K/mTOR pathway." (PMID 36959101, 2023). "In thyroid and prostate cancer studies, autophagy was shown to promote tumor metastasis through Wnt/β-catenin and AMPK/mTOR signaling pathways." (PMID 37138336, 2023). "Experimental studies have revealed that the intracellular pathways ERK/MEK, Akt-mTOR, NF-kB, WNT and JAK/STAT are involved in the regulation of PD-L1 in prostate cancer." (PMID 37297021, 2023). "Our analyses pinpoint histone deacetylases (HDAC), protein kinase A (PKA), PI3K/mTOR, and Janus Kinase (JAK) as key collateral sensitivities to Snail-mediated enzalutamide resistance in prostate cancer cells." (PMID 37228586, 2023). "Some flavonoids also activated the AMPK and PTEN in non-small lung cancer cells, wherein the AMPK and mTOR played contrary roles in metabolism, while the mTOR-, PI3K-, and Akt-related functional activities were observed in prostate cancer cell lines." (PMID 36982245, 2023). "PI3K/AKT/mTOR signaling pathway activation is highly enriched in CRPC and broadly recognized as a critical driver of prostate cancer and a key therapeutic target." (PMID 37823778, 2023). "Curcumin blocks prostate carcinoma cell invasion and EMT that induced by CAFs and reduce the generation of ROS by inhibiting the monoamine oxidase A (MAOA) /mammalian target of rapamycin (mTOR)/hypoxia-inducible factor-1α (HIF-1α) signaling." (PMID 37191432, 2023). "These analyses identified multiple actionable targets, such as XPO1, PI3K/mTOR, aurora kinases, c-MET, polo-like kinases, and JAK/STAT as synthetic lethalities in Snail+ prostate cancer." (PMID 37228586, 2023). "Among these hits were inhibitors targeting signaling molecules and pathways known to be involved in lineage plasticity and prostate cancer therapy resistance, such as aurora kinase, c-MET, and mTOR/PI3K." (PMID 37228586, 2023). "In multiple cancers including prostate cancer, the PI3K/AKT/mTOR signaling pathway was found to be aberrantly activated (Pungsrinont, Kallenbach & Baniahmad, 2021)." (PMID 36132221, 2022). "IGF-1 driven cross-communication between Akt/mTOR and FAK-integrin signaling has been demonstrated in the androgen-resistant prostate cancer cell lines DU145 and PC3." (PMID 35053528, 2022).
prostate carcinoma (continued). "LncRNA Small Nucleolar RNA Host Gene 1 (SNHG1) activates Wnt/β-catenin and PI3K/Akt/mTOR signaling pathways by targeting EZH2 (Enhancer of zeste homolog 2), and promoting proliferation, apoptosis and autophagy of prostate cancer (PCa) cells." (PMID 35309939, 2022). "With regards to the radio-resistance feature of prostate cancer cells, HULC induces MTOR signaling, while it diminishes levels of BECN1, leading to autophagy inhibition." (PMID 35317831, 2022). "A key role in prostate cancer growth activity is played by the insulin growth factor 1 receptor (IGF-1R) with subsequent phosphorylation of the downstream targets, Akt and mechanistic target of rapamycin (mTOR)." (PMID 35053528, 2022). "Prostate cancer cells treated with metformin showed increased expression of REDD1, promoting mTOR inhibition and cell cycle arrest." (PMID 36672573, 2022). "Consistent with the present investigation, in prostate cancer cells, SHI effectively inhibited phosphorylation levels, i.e., activated AKT and mTOR." (PMID 35267423, 2022). "Akt-mTOR inactivation, SphK1 downregulation, ceramide level increase, and oxidative injury were detected in GNE-493-treated prostate cancer xenograft tissues." (PMID 35296639, 2022). "We find that MBNL1-AS1 has been reported to inhibit the progression of prostate cancer by sponging miR-181a-5p and regulating PTEN/PI3K/AKT/mTOR signaling and PTEN signaling happens to be regulated by PLK1, PAF, YB-1, TWIST, YY1, KLF4, and SALL4." (PMID 35518784, 2022). "It has been demonstrated that calmodulin affects autophagy in prostate cancer cells via AKT/mTOR and also participates in PLCγ1-dependent ECM synthesis via the mTOR/P70S6K pathway." (PMID 35494053, 2022). "These proteins are components of the mTOR (mammalian target of rapamycin) and VEGF (vascular-endothelial growth factor) signaling pathways that are involved in prostate cancer development." (PMID 35741059, 2022). "In the same line of evidence, GOLM1 stimulates prostate cancer migration and invasion by triggering the PI3K/AKT/mTOR signaling pathway." (PMID 35805075, 2022). "Mechanistically, SGK1 induces MTOR signaling to inhibit FOXO3 phosphorylation, leading to a decrease in apoptosis and autophagy in prostate cancer cells." (PMID 35317831, 2022). "The PI3K/Akt/mTOR signaling pathway is overactivated in 92% of T-ALL cell lines, and is also dysregulated in 42% of primary prostate cancer samples and 100% of CRPCs." (PMID 35629355, 2022). "Accordingly, the apparent lack of significance of the protein phosphatase activity of PTEN in prostate tumour supprssion supports, and provides insight into, existing efforts to treat prostate cancers with small molecule inhibitors of PI3K, AKT and mTOR." (PMID 36291720, 2022). "For instance, MIR139 induces MTOR signaling, while downregulating BECN1 to inhibit autophagy flux, resulting in subsequent apoptosis induction in prostate cancer cells." (PMID 35317831, 2022). "AKT is an important target and prognostic marker in prostate cancer and signification overexpression of AKT1, AKT2 and mTOR genes was observed in human prostate cancer samples compared with normal prostate gland tissue." (PMID 36936272, 2022). "The study indicated that two major pathways involved in prostate cancer progression, PI3K/Akt/mTOR, and Ras/MAPK, intersect at the eukaryotic transcription initiation factor eIF4E." (PMID 35982949, 2022). "Such upregulation in prostate cancer promoted the proliferation and progression of cancer cells by activating PI3K/AKT/mTOR signaling, thereby being recognized as a biomarker in detecting prostate cancer and evaluating its aggressiveness." (PMID 36468024, 2022). "Dysregulated phosphorylation and tensin homolog cancer suppressor gene (PTEN) expression has frequently been observed in prostate cancer, and this dysregulation induces the aberrant activation of AKT pathway members, including mTOR." (PMID 35163369, 2022).
prostate carcinoma (continued). "Within the context of prostate cancer, the PI3K–Akt–mammalian target of rapamycin (mTOR) pathway is one of the most frequently activated pathways, with genomic alterations occurring in approximately 50% of patients with prostate cancer." (PMID 36305957, 2022). "Silencing SGK1 inhibits MTOR signaling, providing conditions for FOXO3 phosphorylation, and subsequent induction of apoptosis and autophagy in prostate cancer cells." (PMID 35317831, 2022). "mTOR also acts as a mediator in the crosstalk between PI3K/Akt and AMPK pathways and in PC-3 prostate cancer cells, Ag NPs were found to activate autophagy through the AMPK-mTOR pathway." (PMID 36365094, 2022). "Prostate cancer growth and invasion are thus controlled by a fine-tuned network between IGF-1 driven integrin-FAK signaling and the Akt-mTOR pathway." (PMID 35053528, 2022). "Our previous article showed that Cur inhibited the malignant progression of prostate cancer and regulates the PDK1/AKT/mTOR pathway by targeting miR-9." (PMID 35942374, 2022). "In prostate cancer cells, the knockdown of Pkm2 induced autophagic cell death via the AKT/mammalian target of the rapamycin (mTOR) pathway." (PMID 36555159, 2022). "On the other hand, MLST8 stabilizes the raptor-MTOR interaction and promotes mTORC1 activity, and upregulation of MLST8 enhances mTORC1/2 activities in colon carcinoma and prostate cancer." (PMID 34529665, 2021). "HCG11 was reported to work as an anti-oncogene in prostate cancer by sponging miR-543 and modulating AKT/mTOR pathway." (PMID 33402177, 2021). "The main drivers of prostate cancer progression, such as AR, PTEN/PI3K/AKT/mTOR, STAT3, NKX3.1 are influenced by PTMs, which changes their activity, expression, stability, and localization." (PMID 33572160, 2021). "AMPK inhibition had a minor impact on the metformin effect, which induced mTOR inhibition and cell cycle arrest through REDD1 in prostate cancer cells." (PMID 33578894, 2021). "Another study reported that luteolin reduced cell viability and induced apoptosis in prostate cancer cells, besides, it downregulated AKT, ERK, mTOR, and P70S6K." (PMID 34049576, 2021). "Treatment of prostate cancer cells with fisetin suppresses mTOR activity and downregulates the subunits Raptor, Rictor, PRAS40 and GβL, in addition to activating the mTOR repressor tuberous sclerosis complex 2 (TSC2)." (PMID 34575981, 2021). "We also verified this finding in prostate cancer cell lines that overexpression of SIRT6 increased the levels of p-S6, p-S6K, which were downstream of mTOR pathway." (PMID 33995674, 2021). "A low concentration of curcumin has been shown to potently reduce the proliferative and invasive activity of androgen-independent prostate cancer cells by interfering with the CDK-cyclin, the Akt-mTOR pathway, and integrin-related signaling." (PMID 34576132, 2021). "DNA repair pathway, PI3K/AKT/mTOR pathway, BRAF-MAPK and Wnt signaling pathway and activation by glucocorticoid receptors can restore downstream signaling in prostate cancer by alternative proteins." (PMID 34771580, 2021). "In human prostate cancer cells, shikonin inhibited cell metastasis by reducing MMP2/MMP9 expression via AKT/mTOR and ROS/ERK1/2 pathways." (PMID 34812264, 2021). "On the other hand, some studies have suggested that mTOR complexes regulate EMT via RhoA and Rac1 signaling pathways in prostate cancer." (PMID 33920031, 2021). "The targeting of mammalian target of rapamycin (mTOR) kinase and PTEN/PI3K/Akt are an important strategy to prevented from the proliferation of prostate cancer." (PMID 33473265, 2021). "Ursolic acid-induced autophagy in PC3 prostate cancer cells is mediated by the Beclin1 and AKT/mTOR pathways." (PMID 34575981, 2021). "In prostate cancer, AMD1 regulates the mTOR pathway to influence tumor cell proliferation, thus promoting tumor development." (PMID 33413205, 2021).
prostate carcinoma (continued). "PARP inhibitors are paving the way of precision medicine in prostate cancer, followed by drugs targeting the PI3k AKT mTOR pathway." (PMID 33781305, 2021). "The effects of mTOR on HIF-1 stabilization and transactivating functions was also reported in prostate cancer cells cultured under hypoxic conditions." (PMID 34199959, 2021). "Dual PI3K/mTOR inhibition with BEZ235 in patient-derived OSCC cells or prostate cancer cell lines.Treatment of OSCC cell lines with RAD001 inhibitor decreases the phosphorylation and activation of mTOR and increases the RR." (PMID 34900673, 2021). "Another research reported that AR/mTOR axis promoted the expression and activity of SREBP1, lead to androgen-dependent de novo synthesis of lipid and facilitated growth of prostate cancer (PCa) cells." (PMID 34041015, 2021). "Augmented phosphorylation/activation of key PI3K-AKT-mTOR pathway components (e.g., p-AKT and p-mTOR) has been shown to correlate with prostate cancer progression in the clinic." (PMID 32630372, 2020). "The mTOR inhibitor CCI779 showed anti-cancer activity in colorectal carcinoma and prostate cancer cases; here, we also showed the anti-cervical cancer effects of CC1779 in vitro and in vivo." (PMID 33396624, 2020). "Overall, these findings demonstrated a synergistic role of endothelial cells in contributing to prostate cancer proliferation and chemoresistance via inducing ERG expression and activating the Akt/mTOR signaling pathway." (PMID 33425737, 2020). "Remarkably, PTEN counteracts the glyoxalase dependent PI3K/AKT/mTOR/p-PKM2(Y105)-axis inducing an elevated glycolytic rate and cell proliferation in prostate cancer." (PMID 32708484, 2020). "Our study investigated the role and mechanism of cir-ITCH in PCa and provided evidence indicating that cir-ITCH functions as tumor suppressor in prostate cancer cells via the Wnt/β-catenin and PI3K/AKT/mTOR pathways in an AR-independent manner." (PMID 32904490, 2020). "A hexane fraction of guava leaves (Psidium guajava L.), which contained 3.76% α-patchoulene, inhibited the AKT/mTOR/S6K1 signaling pathway and induced apoptosis in prostate cancer cells." (PMID 32963578, 2020). "PTEN is one of the most commonly altered tumor suppressor genes in prostate cancer, which negatively regulates the PI3K/AKT/mTOR signaling pathway." (PMID 32264916, 2020). "The objective of the study was to study the PR expression in patients with benign prostatic hyperplasia and prostate cancers in connection with the transcription, growth factors, AR, ERα, ERβ, and components of the AKT/mTOR signaling pathway expression." (PMID 32102520, 2020). "In prostate cancer, PRRT3-AS1 silencing can block the mTOR signaling pathway, promote tumor cell autophagy, and inhibit tumor cell proliferation." (PMID 32851059, 2020). "In human prostate cancer cells, CDDO-Me inhibits the activity of p-Akt and mTOR and of their downstream targets and overexpression of Akt leads to resistance to CDDO-Me." (PMID 31766211, 2019). "In preclinical studies, the dual PI3K/mTOR inhibitors BEZ235 and GDC-0980 demonstrated effective inhibition of cell proliferation in prostate cancer cells." (PMID 30754640, 2019). "GAS5 silencing induces resistance to, and ectopic GAS5 expression confers sensitivity to, the cytostatic effects of mTOR inhibitors, thereby demonstrating a role for GAS5 lncRNA in mTOR inhibitor action in prostate cancer." (PMID 31533355, 2019). "Our experimental results showed that AICAR enhances the expression of TSC1 and TSC2, whereas it reduces the expression of mTOR and MYC as well as decreases the phosphorylation of p70S6K in 22Rv1 prostate cancer cells." (PMID 30987073, 2019).